RELA (RELA proto-oncogene, NF-kB subunit)
Diseases named in the same sentence as RELA in open-access papers (continued):
Sharing a sentence is not in itself a finding about the gene and the disease.
inflammatory bowel disease (8 papers, 2022 to 2025). A spectrum of small and large bowel inflammatory diseases of unknown etiology. "Abnormal inflammation associated with inflammatory bowel disease is caused by excessive activation of RELA/NF-κB." (PMID 36925608, 2023). "Topological analysis identified 14 core targets based on centrality metrics, and five key intersection genes (CASP7, BIRC5, CDK9, STAT1, RELA) were highlighted as significantly associated with core network functions, including inflammatory bowel disease and apoptosis." (PMID 41515060, 2025). "The RELA protein is treated as a potential cancer biomarker, responsible for cytokine production and inflammatory bowel disease, when AKT1 is a protein that aids in the correct growth and operation of the nervous system." (PMID 37993790, 2023). "The core pathway related to UC was inflammatory bowel disease referring to IL6, TNF, RELA, and STAT3." (PMID 36382627, 2022). "Among these, the core pathway related to UC was inflammatory bowel disease (KEGG:05321), containing the hub targets of IL6, TNF, RELA, and STAT3." (PMID 36382627, 2022).
ischemia (8 papers, 2012 to 2024). A hypoperfusion of the BLOOD through an organ or tissue caused by a PATHOLOGIC CONSTRICTION or obstruction of its BLOOD VESSELS, or an absence of BLOOD CIRCULATION. "Nuclear factor-kappa B (NF-κB) is a transcription factor comprised of p50, RelA/p65, c-Rel, RelB, and p52 subunits that can regulate growth and elaboration of neural processes, and protect neurons against ischemia-induced neurodegeneration." (PMID 31673241, 2019). "The c-Rel subunit has been shown to play a protective role, whereas RelA activation overrides that resulting in increased neuronal damage after ischemia." (PMID 24265774, 2013). "However, specific knockout of the RelA gene in animal models has demonstrated a decrease in both systemic ischemia-reperfusion injury and local injury resulting from branch coronary artery obstruction." (PMID 38935597, 2024). "Our studies have shown that mechanisms affecting the acetylation state of RelA might discriminate between protective and neurotoxic activation of NF-κB during ischemia." (PMID 26042083, 2015). "Neurotoxic stimuli, such as ischemia, glutamate, β-amyloid, or 1-methyl-4-phenylpyridinium (MPP+), induce p50/RelA dimers activation and the transcription of a panel of pro-apoptotic genes." (PMID 26042083, 2015). "Neurotoxic stimuli, including ischemia, glutamate, β-amyloid, or 1-methyl-4-phenylpyridinium (MPP+) induce the activation of p50/RelA dimer and the transcription of pro-apoptotic factors, such as Bim and Noxa." (PMID 36339574, 2022). "Intriguingly, in the basal ganglia of aged c-Rel deficient mice, but not in aged matched controls, the acetylation state of RelA was reminding the one observed in lethal ischemia." (PMID 26042083, 2015). "The TfR was not responsive in early OGD phases, even after RelA over-expression, agreeing with previous reports linking TfR activation to the late phase of ischemia and reperfusion." (PMID 22666436, 2012).
liver cancer (8 papers, 2016 to 2025). An epithelial or non-epithelial malignant neoplasm that arises from the liver. "Beyond the PI3K/AKT core, network pharmacology analysis uncovered 185 overlapping targets, including inflammatory regulators NFKB1 and RELA, suggesting that cinnamic acid may enhance its anti-liver cancer effect by inhibiting the tumor-associated inflammatory microenvironment." (PMID 40872596, 2025). "There was no apparent relationship of PD-L1 with RelA or RelB in liver cancer." (PMID 35177112, 2022).
neuroblastoma (8 papers, 2012 to 2023). Neuroblastoma (NB) is the most common solid, extracranial childhood tumor. "Thus, we assessed whether the combination of MG132 and RA modulates NF-κB signalling in neuroblastoma cells by quantifying nuclear anti-RelA antibody staining for each treatment condition." (PMID 24116151, 2013). "The quantification of the number of mRNA copies of RelA and RelAp43 was performed in several cell lines of human origin: HeLa cells, a cervical carcinoma cell line; 293T cells derived from embryonic kidney; SK-N-SH and IMR5, neuroblastoma cell lines." (PMID 23271966, 2012). "In addition, we verified that RELA was not involved in CD271 expression in neuroblastoma or normal epithelial cell lines, which differed from a previous study suggesting that Sp1 is important for CD271 transcription in neuroblastoma cells." (PMID 36273237, 2022). "Specifically, we found that RELA promoted CD271 transcription in squamous cell carcinoma cell lines but not in normal epithelium and neuroblastoma cell lines." (PMID 36273237, 2022). "However, in normal esophageal epithelium (Het-1A) and a neuroblastoma cell line (IMR-32), RELA knockdown did not affect CD271 expression, despite confirmation of decreased RELA levels." (PMID 36273237, 2022).
pancreatic adenocarcinoma (8 papers, 2007 to 2025). "Based on the association of class I HDAC expression and nuclear RelA/p65 translocation in pancreatic adenocarcinoma in vivo and the fact that RelA/p65 is a putative target of HDIs we wanted to know if this link could be functionally confirmed for pancreatic cancer in vitro." (PMID 19912635, 2009). "Overexpression of RELA has been reported in pancreatic adenocarcinomas and correlated with the activation of NF-κB pathway." (PMID 27354262, 2016). "In a different series of 82 pancreatic adenocarcinomas a strong cytoplasmic or nuclear expression of RelA/p65 was observed in 42 and 37 samples, respectively." (PMID 23641216, 2013). "To provide this missing translational link, we analysed expression of RelA/p65 in 82 pancreatic adenocarcinomas by immunohistochemistry." (PMID 17622249, 2007). "Cytoplasmic and nuclear overexpression of RelA was evident in a subset of pancreatic adenocarcinomas." (PMID 17622249, 2007). "Here, we found the NF-κB subunit RelA to be overexpressed in roughly half of a large set of pancreatic adenocarcinomas analysed." (PMID 17622249, 2007). "The expression levels of CTNNB1, RELA, TWIST1, and YAP1 in pancreatic adenocarcinoma (PAAD) tissues were higher than those in corresponding normal tissues." (PMID 40124511, 2025). "A previous report indicates that RelA, the p65 subunit of NF-κB, is constitutively activated in 67% (16 of 24) of pancreatic adenocarcinomas but not in normal pancreatic tissues." (PMID 24340014, 2013). "And in fact RELA amplification has been described in various solid tumours, but not in ductal pancreatic adenocarcinomas." (PMID 17622249, 2007).
subependymoma (8 papers, 2017 to 2024). Subependymoma is a rare and slow growing type of ependymoma, often presenting in middle-aged adults, found more commonly in men than in women, usually located in the fourth and lateral ventricles and manifesting with variable symptoms including headache, nausea, and loss of balance. "It has been proposed that ST-EPNs may be divided into three molecular subgroups; ST-EPN-RELA (RELA fusion-positive), ST-EPN-YAP1 (YAP1 fusion-positive) and ST-SE (subependymoma)." (PMID 30514397, 2018).
autoimmune disease (7 papers, 2017 to 2025). A disorder resulting from loss of function or tissue destruction of an organ or multiple organs, arising from humoral or cellular immune responses of the individual to their own tissue constituents. "Given the ubiquitous nature of the NF-κB signaling pathway and its involvement in the regulation of hundreds of target genes, RelA deficiency may also present with autoimmune diseases owing to its potential impact on inflammatory responses, autoimmunity, and carcinogenesis." (PMID 40134438, 2025). "PDLIM2 suppresses Th1 and Th17 cell differentiation through inhibition of STAT3/4 and RelA in autoimmune disease, indicating that PDLIM2 plays a crucial role in T cell-mediated immune responses." (PMID 35707002, 2022). "Thus, it would be of strong interest to be able to target RelA in Tregs to propose new therapies triggering or inhibiting Tregs in autoimmune diseases or cancer, respectively." (PMID 31749798, 2019). "RELA and RELB are key TFs of the NFκB pathway, and their reduced expression leads to dysregulation of the NFκB pathway, resulting in severe autoimmune diseases and reduced immunity." (PMID 38192721, 2023). "FOXP3, RORγt, STAT3, RelA/p65 (NF-κB), and c-Fos/c-Jun (AP-1) are transcription factors targeted by SIRT1, which are well-studied and are crucial to a balanced immune system, but the role of SIRT1 in autoimmune disease is only in the incipient stage, especially in the progression of SLE." (PMID 33981300, 2021).
cervical carcinoma (7 papers, 2012 to 2025). A carcinoma arising from either the exocervical squamous epithelium or the endocervical glandular epithelium. "Previously, several reports have described the activation of RELA in precancerous lesions of the cervix and cervical cancer tissues." (PMID 40141137, 2025). "By analyzing the differential expression of CXC chemokines in cervical cancer, we identified three key transcription factors (RELA, NFKB1 and SP1)." (PMID 34321012, 2021). "RelA K310 acetylation was lower in all three cervical cancer cell lines than in uninfected KCs." (PMID 26055519, 2015). "In contrast to these findings, another study demonstrated that cucurbitacin B did not affect TNF-α-induced nuclear RelA translocation but inhibited its transcriptional activity in human cervical carcinoma HeLa cells." (PMID 35806134, 2022). "Cucurbitacin B was shown to down-regulate the TNF-α-induced expression of NF-κB target genes and inhibit the transactivation activity of RelA without suppressing its nuclear translocation in human cervical carcinoma HeLa cells." (PMID 35806134, 2022). "The nuclear positivity rate of RELA (representing the degree of NF-κB activation) in CIN and CSCC cells reported by different studies varies greatly, and it remains unclear when NF-κB is activated during the transformation from cervical intraepithelial neoplasia to cervical cancer." (PMID 40141137, 2025).
non-small cell lung carcinoma (7 papers, 2015 to 2024). A group of at least three distinct histological types of lung cancer, including non-small cell squamous cell carcinoma, adenocarcinoma, and large cell carcinoma. "Nuclear factor (NF)-κB signalling is required for lung adenocarcinoma development in mice, and both of its subunits RelA and RelB were independently reported to be highly expressed in human non-small cell lung cancer (NSCLC)." (PMID 26147201, 2015). "A previous study of non-small cell lung cancers indicated that miR-124 helped to regulate autophagy, NF-kappa signaling, and cell viability, and that suppression of p62 expression by miR-124 was correlated with the NF-kappa subunit, RELA/p65." (PMID 32391561, 2020). "Although HOXA9 has been reported to regulate RELA expression in Non-small Cell Lung Cancer, no report has demonstrated such regulation is direct or indirect." (PMID 31683603, 2019).
Obesity (7 papers, 2019 to 2024). Accumulation of substantial excess body fat. "As the key regulators of NFKB signaling, NFKB and RELA were believed as potential targets to overcome the problem of obesity." (PMID 36034923, 2022). "This analysis highlighted an increase in pro-inflammatory cytokines TNF-α and IL-6 and upregulation of NF-κB-related genes NFKB1 and RELA in obesity." (PMID 35215414, 2022). "In the AT-SVF macrophages, nuclear RelA was enhanced in the HFD-induced obesity group in relation to the LFD group (fold change significantly higher than one), while nuclear cRel was not significantly affected." (PMID 31316525, 2019). "The study further shows that the effects of diet on TNF-α/IL-10 ratios were linked to distinct patterns of NF-κB accumulation in the nucleus: while RelA was the NF-κB subunit most impacted by obesity in adipose tissue macrophages, cRel was the subunit affected in peritoneal macrophages." (PMID 31316525, 2019). "By establishing a gene interaction network, we found that certain TFs (RELA and NFKB1) and miRNAs (has-miR-195-5p and has-miR-106a-5p) may play key roles in the development of obesity and GC." (PMID 39011399, 2024). "Findings demonstrated that characteristics of systemic inflammation in obesity, including elevated pro-inflammatory cytokine production (TNF-α and IL-6) and upregulated NF-κB-related genes (NFKB1 and RELA), present in obesity were reduced by significant weight loss and ex vivo SCFA treatment." (PMID 35215414, 2022). "Few studies have analysed NFKB1, RELA and MAPK1 mRNA expression in obesity." (PMID 35215414, 2022). "On the other hand, in peritoneal macrophages, obesity significantly boosted the nuclear accumulation of cRel, without exerting any effect or trend to an effect on RelA or RelB." (PMID 31316525, 2019). "Moreover, bulk RNA-Seq revealed an enhanced transcriptional response to LPS at T3 relative to T1 in the lean subjects relative to those with obesity marked by higher expression of pro-inflammatory molecules (IL6, IL1B, TNF) and induction of transcription factors (RELA, IRF1, STAT3)." (PMID 34195568, 2021).
osteoarthritis (7 papers, 2018 to 2024). A noninflammatory degenerative joint disease occurring chiefly in older persons, characterized by degeneration of the articular cartilage, hypertrophy of bone at the margins and changes in the synovial membrane. "NF-κB complex played a vital role in progression of osteoarthritis through RELA and VCAM1 which was linked with osteoarthritis as a precursor." (PMID 29731966, 2018). "Of note, STAT3, RELA, and NFKB1 transcription factors identified are considered players in key pathogenic signaling pathways in osteoarthritis." (PMID 38938688, 2024). "Increase in RELA/p65 protein level and activity were reported in the inflamed synovium of osteoarthritis (OA) and RA patients." (PMID 35529852, 2022). "The predicted pathway also correlated the Histone Deacetylase 2 (HDCA2) with IL6 and MMP9 and RELA which was seem to be boost the progression of osteoarthritis by repressing cartilage specific gene." (PMID 29731966, 2018). "The addition of Wharton’s jelly to synoviocytes isolated from human knees with grade IV osteoarthritis reduced the expression of MMP-13 and RELA." (PMID 34832872, 2021). "For instance, a positive relationship has been identified between RELA expression and MMP-13 expression, a cytokine involved in cartilage degradation, in synoviocytes affected by osteoarthritis." (PMID 33207573, 2020). "Moreover, several transcription factors upstream of the stretch gene signature, identified by in silico analysis here (STAT3, RELA, and NFKB1), mediate osteoarthritis signaling pathways." (PMID 38938688, 2024). "Our protocol could be easily transferred to primary human chondrocytes harvested from osteoarthritis (OA) patients, human FE002 chondroprogenitor cells, bovine chondrocytes, and a human chondrocyte cell line, achieving comparable mean RELA KO editing levels using the same protocol." (PMID 38468277, 2024).
periodontitis (7 papers, 2020 to 2026). An acute or chronic inflammatory process that affects the tissues that surround and support the teeth. "In addition to improving our understanding of the molecular causes of periodontitis, this method enables the prioritization of transcriptional regulators essential for inflammation and bone resorption, including STAT3, RELA, and NF- κB." (PMID 41050338, 2025). "An increased expression of RELA, the p65 subunit of the NF-kappa-B complex which regulates DNA transcription, cell survival, and immune response to infection, were also revealed in gingival tissue affected by periodontitis in T2D patients." (PMID 35885959, 2022). "Notably, four of the cluster A genes, specifically, CBL, GRB2, PIK3R1, and RELA, were also ranked among the five leader genes previously identified in periodontitis." (PMID 32962181, 2020). "Moreover, a bi-directional relationship is suggested by several authors because of the increased production of pro-inflammatory cytokines such as IL1B, IL4, IL6, IL10, CBL, and RELA, which are often present in the periodontitis development and CRC carcinogenesis." (PMID 39517401, 2024). "Transcriptomic network analysis has identified transcription factors (TFs), including NF-κB (NFKB1/RELA), AP-1 (FOS/JUN), and STAT3, as master regulators in periodontitis, highlighting their recent relevance." (PMID 41050338, 2025). "It is predicted that PTGS2 and BCL2 are the most important targets of the Asarum–Angelica drug pair for regulating periodontitis, and AKT1, CASP3, BAX, RELA, etc., are also relatively important targets." (PMID 38139216, 2023).
chronic lymphocytic leukemia (6 papers, 2020 to 2025). "For example, rs539846 located in a SE affects chronic lymphocytic leukemia susceptibility through differential binding to RELA (NF-kappa-B subunit) and direct modulation of BMF expression, impacting the antiapoptotic protein B cell lymphoma 2 (BCL2)." (PMID 38410974, 2024). "For instance, the NF-κB subunit RelA (p65) was an independent prognostic marker of survival with the capacity to predict the duration of response to therapy in chronic lymphocytic leukemia." (PMID 37895229, 2023).
Insulin resistance (6 papers, 2013 to 2025). Increased resistance towards insulin, that is, diminished effectiveness of insulin in reducing blood glucose levels. "Curcumin improved peripheral insulin resistance in insulin-resistant ob/ob mice with steatosis by reducing NF-κB/RelA DNA-binding activity, decreasing mRNA level of TNF and IL-6, and enhancing IL-4 production in hepatic TNF/iNOS-producing dendritic cells and adipose tissue macrophages." (PMID 24348712, 2013). "An integrated system pharmacology analysis then revealed that various targets such as PPARG, RELA, EGFR and numerous pathways such as TNF signalling, PI3K-Akt signalling, MAPK signalling and NF-κB signalling were involved in the underlying mechanisms of GQD in improving diabetic insulin resistance." (PMID 36187136, 2022).